APP (amyloid beta precursor protein)
Diseases named in the same sentence as APP in open-access papers (continued):
Sharing a sentence is not in itself a finding about the gene and the disease.
neuroblastoma (continued). "We found that each of the APP 5′UTR inhibitors lowered Aβ secretion from SH-SY5Y neuroblastoma cells, albeit at levels near the limits of detection for Aβ (pg/ml range)." (PMID 23935819, 2013). "Remarkably, a cluster of four E4BP4 sites in intron 4 of human APP exists in actively transcribing chromatin in a human neuroblastoma cell-line, SHSY5Y, expressing APP as shown using chromatin immunoprecipitation (ChIP) experiments." (PMID 22947103, 2012). "We performed co-immunoprecipitation from mouse neuroblastoma N2a cells stably or transiently transfected with human APP and human PrP, respectively." (PMID 23236467, 2012). "AICD strongly down regulated GD3S transcription and knock-in of an AICD deletion mutant of APP in vivo, or knock-down of Fe65 in neuroblastoma cells, was sufficient to abrogate normal GD3S functionality." (PMID 22470521, 2012). "The effect of F. macrophylla on Aβ metabolism was detected using the cultured mouse neuroblastoma cells N2a transfected with human Swedish mutant APP (swAPP-N2a cells)." (PMID 22719789, 2012). "This is consistent with our observation that Sw-APP transfected and wt-APP transfected neuroblastoma cells overproducing Aβ have increased NF-κB activation than empty-vector transfected cells not overproducing Aβ." (PMID 23300647, 2012). "Increased expression of LRP10 in human neuroblastoma SH-SY5Y cells induces the accumulation of mature APP in the Golgi and reduces its presence at the cell surface and its processing into Aβ, while knockdown of LRP10 expression increases Aβ production." (PMID 22734645, 2012). "It is likely that Aβ neurotoxicity in the Sw-APP transfected neuroblastoma cells induces mitochondrial dysfunction leading to decreased ATP level, hence stimulates AMPK activation." (PMID 23300647, 2012). "In order to validate these observations in more physiological conditions, we transfected our candidate pre-miRs into mouse neuroblastoma Neuro2A cells, a model previously used to study neuronal APP expression regulation by miRNAs." (PMID 21982160, 2011). "EGCG similarly protects SH-SY5Y human neuroblastoma cells from amyloid precursor protein (APP), 3-hydroxykynurenine, or 6-hydroxydopamine (6-OHDA) toxicity, and rescues rat PC12 cells from serum withdrawal or paraquat-induced apoptosis." (PMID 21060289, 2010). "In this paper, we demonstrate that HSV-1 interferes with APP processing in SH-SY5Y human neuroblastoma cells and rat cortical neurons." (PMID 21085580, 2010). "We found that infection of SH-SY5Y human neuroblastoma cells and rat cortical neurons is followed by multiple cleavages of APP, which result in the intra- and/or extra-cellular accumulation of various neurotoxic species." (PMID 21085580, 2010). "To study the effects of lactic acid on APP processing, we chose to use the human neuroblastoma cell line SH-SY5Y." (PMID 21072203, 2010). "In contrast, our study used a physiologically relevant concentration of lactic acid to stimulate neuroblastoma cells that endogenously express wild-type APP, small amounts of Grp94 and moderate amounts of Grp78 under unstimulated conditions." (PMID 21072203, 2010). "To discover novel APP-selective inhibitors of gamma-secretase, we developed cell-free assays employing recombinant APP or Notch substrates incubated with an enriched enzyme preparation derived from IMR-32 neuroblastoma cells." (PMID 21190552, 2010). "The APP-Gal4VP16/Gal4-reporter screen was stably incorporated into neuroblastoma cells in order to assay γ-secretase mediated APP proteolysis under normal and pharmacologically induced ER stress conditions." (PMID 20161760, 2010). "Aβ containing CM were obtained from Chinese Hamster Ovarian (CHO) and human neuroblastoma SH-SY5Y cells expressing wild type APP, and human embryonic kidney 293 (HEK293) cells expressing familial AD-linked Swedish mutant APP." (PMID 19480719, 2009).
neuroblastoma (continued). "The human neuroblastoma cell line SH-SY5Y was stably transfected with constructs coding for the APP C-terminal fragment C99WT, moreover with constructs bearing the point mutations C99I45F and C99V50F and the vector control (mock-transfected, negative control)." (PMID 19707560, 2009). "To examine the effects of latrepirdine on Aβ generation in vitro, we treated neuroblastoma (N2a) cells stably overexpressing Swedish APP for 6 hours either in the absence (vehicle) or presence of latrepirdine (ranging from 500 pM to 5 μM, as indicated)." (PMID 20017949, 2009). "Mouse N2a neuroblastoma cells overexpressing Swedish APP were incubated for 6 hr in the presence of either vehicle or vehicle + latrepirdine (500pM-5 μM)." (PMID 20017949, 2009). "We use an AICD-Gal4 mediated luciferase expression assay as a general reporter of APP metabolism in the human neuroblastoma cell lines, SH-SY5Y." (PMID 17718916, 2007). "We demonstrate for the first time that Ubiquilin 1 regulates APP metabolism in the human neuroblastoma cell line, SH-SY5Y." (PMID 17718916, 2007). "Taking advantage of the APP intracellular domain's (AICD) ability to activate transcription, we established an assay to monitor APP metabolism in the human neuroblastoma cell line, SH-SY5Y." (PMID 17718916, 2007). "In order to find if HSV1 directly affects APP and its degradation, we have examined this protein from human neuroblastoma cells (normal and transfected with APP 695) infected with the virus, using Western blotting." (PMID 16109164, 2005). "By contrast, overexpression of SORL1 displayed enhanced endosomal recycling through redirection of APP to the Golgi-network, thus blocking APP processing and reducing Aβ peptide levels in neuroblastoma, mouse and human induced pluripotent stem cell (hiPSC)-derived neuronal models." (PMID 38368934, 2024). "The neuroblastoma cell line SH-SY5Y is a well-established model for the differentiation of cells into cortical-like neurons and was used to evaluate the single and double loss-of-function of CNTN4 and APP on neuronal differentiation in vitro." (PMID 38745463, 2024). "Through shRNA knockdown experiments using in vitro N2a neuroblastoma cultures transfected with human APP, it was shown that reduced CD2AP expression results in a decrease in cell membrane APP, which would suggest less APP being processed in the endosomes and thus decreasing Aβ release." (PMID 38368934, 2024). "Through an in vitro study, Zhang and colleagues investigated how TD affects APP processing in SH-SY5Y neuroblastoma cells that overexpress APP and found that TD promoted maturation of BACE1 and increased β-secretase activity that resulted in elevated levels of Aβ peptides as well as β-CTF." (PMID 36829974, 2023). "However, the profiles of secreted Aβ from endogenous APP and overexpressed APPswe are distinct in mouse neuroblastoma Neuro2a cells." (PMID 36721026, 2023). "Long term OGA inhibition also increased APP protein levels in SH-SY5Y neuroblastoma cells." (PMID 37469955, 2023). "Indeed, iron levels were shown to regulate mRNA translation of APP holo-protein in astrocytes and neuroblastoma cells by a pathway like iron control in the translation of the ferritin-L and -H mRNAs by IREs in their 5′UTRs." (PMID 36899898, 2023). "Similarly, the anti-apoptotic effects of TUDCA were also seen in vitro model of familial AD by expressing APP with the Swedish mutation, or double-mutated human APP and PS1 in mouse neuroblastoma cells." (PMID 37308953, 2023). "MiR-455-3p can decrease APP levels in a mouse neuroblastoma cell line." (PMID 38003448, 2023). "In this direction, we have previously shown that downregulation of APP in neuroblastoma SH-SY5Y cells interferes with Store-Operated Ca2+ channel (SOC) activity and enhances both ER and acidic store Ca2+ content, all resulting in the upregulation of Ca2+-based signaling networks." (PMID 36768625, 2023).
neuroblastoma (continued). "Furthermore, treatment of N2a-APP cells (mouse neuroblastoma N2a cells that express mutant human APP) with alcohol (412 mM) and APOE4 (7.5 μg/mL) exacerbated neuronal apoptosis and elevated cellular oxidative stress." (PMID 37298443, 2023). "Previous treatment of human neuroblastoma cells with NAC diminished β-amyloidogenesis induced by two oxysterols suggesting that this antioxidant can protect against cholesterol oxidation products modulating APP and β-secretase activity in the brain." (PMID 35204298, 2022). "We co-transfected neuroblastoma N2a cells with APP:YFP and BACE1:CH." (PMID 35445022, 2022). "Furthermore, these authors also demonstrated that EVs derived from neuroblastoma cells when injected centrally into APP over-expressing mice resulted in reduced synaptotoxicity and Aβ levels." (PMID 35421203, 2022). "Likewise, in vitro studies with NAC in cultured neuroblastoma cells affected APP metabolism by modifying β-secretase and γ-secretase actions and reduced phosphorylated tau concentrations in the absence of stressful conditions." (PMID 35204298, 2022). "Bioenergetic parameters and amyloid precursor protein (APP) processing products were investigated in vitro in human neuroblastoma SH-SY5Y-APP695 cells, expressing neuronal APP, and in vivo, in the invertebrate Caenorhabditis elegans (CL2006 & GMC101) expressing muscular APP." (PMID 35955803, 2022). "Furthermore, NAC inhibits APP gene transcription in neuroblastoma cells by reducing the crucial activity of NF-kB." (PMID 35204298, 2022). "The standardized extract from the leaves of Gingko biloba tree, EGb761, prevented β-amyloid fibril formation in solution in vitro as well as in the conditioned medium of neuroblastoma cells stably expressing the Swedish mutant APP and the exon-9 deletion mutant PS1." (PMID 36428494, 2022). "Besides DHA, both the n-3 PUFA eicosapentaenoic acid (EPA) and the n-6 PUFA AA increased α-secreted APP (sAPPα) in differentiated human neuroblastoma SH-SY5Y cells." (PMID 36428494, 2022). "Furthermore, predominant mitochondrial fragmentation and decreased levels of DRP1 upon overexpression of APP in M17 neuroblastoma cells have been reported by the same group 91." (PMID 34522215, 2021). "We measured the UPR dynamic response in three human neuroblastoma cell lines overexpressing the wild-type and two familial AD (FAD)-associated mutant forms of amyloid precursor protein (APP), the Swedish and Swedish-Indiana mutations, using gene expression analysis." (PMID 34769426, 2021). "A recent study showed that overexpression of the β-secretase-derived APP-CTF fragment (C99) in neuroblastoma SH-SY5Y cells triggers excessive mitochondrial morphology alterations associated with enhanced mitochondrial reactive oxygen species production independent of Aβ." (PMID 34880748, 2021). "Furthermore, in murine neuroblastoma cells transfected with the human APP mutant, EGCG inhibited the generation of Aβ1–40 and Aβ1–42 by increasing the action of α-secretase, which promotes the non-amyloidogenic processing of APP." (PMID 34594185, 2021). "Herein, we generated a FAD human neural cell culture model that mimicked AD pathology by overexpressing human APP with both Swedish (K670N/M671L) and London (V717I) FAD mutations in a human neuroblastoma cell line to investigate the therapeutic effect of MSC-exosomes in vitro." (PMID 34073900, 2021). "Furthermore, in APPswe Tg mice, proliferation markers, such as PCNA, seem to induce cell cycle re-entry and its mRNA levels have been found to be increased in brain tissue from AD patients and in APP human neuroblastoma SH-SY5Y cells." (PMID 34440085, 2021). "Also decreased expression of BACE-1 and APP was demonstrated after caffeine treatment in human neuroblastoma SH-SY5Y cells exposed to AlCl3 and Aβ." (PMID 33562156, 2021).
neuroblastoma (continued). "The diminution of Pdk4 observed in hAPP-expressing cells indicates that hAPP expression and/or increase in total APP content enhances glycolytic metabolism, as reported in human neuroblastoma cells in which increase in neuronal hAPP levels mediates an Aβ-independent Pdk4 downregulation." (PMID 34228639, 2021). "Furthermore, human neuroblastoma cells treated with TA had significantly decreased protein levels of APP." (PMID 33809987, 2021). "In the current study, we showed that O-GlcNAcylated APP in response to insulin could reduce the localization of APP in lipid rafts using neuroblastoma SH-SY5Y cells expressing APP and BACE1 as well as cultured hippocampal neurons from Sprague Dawley rats." (PMID 34940409, 2021). "Reciprocally, exogenous expression of PGC-1α in N2a neuroblastoma cells could regulate APP processing by downregulating the transcription of BACE1, which effected decreased secreted Aβ and increased non-amyloidogenic soluble APPα." (PMID 32471464, 2020). "Moreover, the intracerebral infusion of EVs isolated from neuroblastoma cells diminishes Aβ pathology and amyloid deposition in APP transgenic mice." (PMID 33362690, 2020). "APP 5′ UTR-directed drugs decreased APP levels in SH-SY5Y neuroblastoma cells." (PMID 33374126, 2020). "The molecular mechanism of the observed capsaicin induced elevated β-secretase cleavage of APP was further examined in neuroblastoma cells by analyzing BACE1 protein levels, gene expression and by performing β-secretase assays in living cells and purified membranes." (PMID 32514053, 2020). "Besides, a neuroblastoma cell line co-transfected with Swedish mutant APP showed a higher Bax/Bcl2 ratio." (PMID 33276671, 2020). "Dividing N2a neuroblastoma cells and human neural stem cells (NSCs) exposed to the cyanobacterial neurotoxin β-N-methylamino-L-alanine (BMAA) generates HS-deficient Gpc-1 and displays increased APP processing." (PMID 32039447, 2020). "The neuroblastoma cell line SH-SY5Y is a commonly used neuronal cell model to study APP processing." (PMID 31953468, 2020). "In vivo, continuous intracerebral infusion of exogenous neuroblastoma-produced EVs apparently trapped and targeted for microglial phagocytosis sufficient Aβ in the brain of APP overexpressing transgenic mice to reduce Aβ levels, amyloid deposition, and synaptotoxicity in the hippocampus." (PMID 31911768, 2019). "In addition, miR-200a-3p relieved the production of Aβ1-42, manifesting that miR-200a-3p protected against the injury derived from the overexpression of APP in the neuroblastoma SH-SY5Y cell line." (PMID 31379578, 2019). "An in vitro study where mouse neuroblastoma cells were transfected with either wild-type APP or APP mutants related to AD, revealed increased levels of bisecting GlcNAc and core fucose N-glycan alterations on APP mutants compared to wild-type APP upon analysis of isolated glycans by HPLC." (PMID 31484367, 2019). "It did, however, immediately and continually suppress rotenone-induced superoxide levels, which may be a result of the reported doubling of manganese superoxide dismutase levels in APP over-expressing neuroblastoma cells." (PMID 30612335, 2019). "To confirm whether the cholesterol level affected endogenous APP localization in lipid rafts from neuronal cells, we used human neuroblastoma SH-SY5Y cells." (PMID 30682043, 2019). "Notably, L-type Ca2+ channel blockers were also found to have neuroprotective effects against Aβ-induced neuronal apoptosis in cultured rat cortical neurons and from amyloid precursor protein (APP)-induced neurotoxicity in neuroblastoma cells." (PMID 31216184, 2019). "The amyloid-beta precursor protein (AbPP), a ubiquitously expressed adhesion and neuritogenic protein, is regulated by reproductive hormones including the gonadotropin luteinizing hormone (LH) in human neuroblastoma cells." (PMID 30124164, 2018).
neuroblastoma (continued). "Interestingly, our results show that cells of the same type (both neuronal and neuroblastoma cells) display different ratios of red/green fluorescence intensity, suggesting that the processing rate of APP is highly variable even within the same population." (PMID 28413720, 2017). "The possibility that α-synuclein and APP may alter one another’s expression was first addressed using SH-SY5Y human neuroblastoma cells, stably overexpressing either protein." (PMID 28187176, 2017). "As an acute in vitro model, mouse neuroblastoma cells (N2a-APP/Swe) were exposed to nPM; pro-amyloidogenic APP processing was assessed as the ratio (sAPPβ/α) of soluble fragments from β-secretase (sAPPβ, pro-amyloidogenic) and α-secretase (sAPPα, non-amyloidogenic)." (PMID 28140404, 2017). "Thus, we created stable murine neuroblastoma cells overexpressing myc-tagged APP (N2a APPmyc), HA-tagged BACE1 (N2a BACE-HA) or HA-tag alone (N2a HA)." (PMID 28005987, 2016). "The present study revealed that APP is either not modified or barely modified in the brain, whereas we previously found that it is modified with bisecting GlcNAc in neuroblastoma cells, indicating that bisecting GlcNAc modification on APP occurs in a limited number of cell types." (PMID 25592972, 2015). "We confirmed that APP was modified with bisecting GlcNAc in C17 neuroblastoma cells, while APP in the brain was not reactive with E4-PHA, suggesting that modification of APP with bisecting GlcNAc occurs in a limited number of cell types and is non-existent or negligible in the brain." (PMID 25592972, 2015). "In 2006, Rajendran and colleagues provided first evidence that (i) Aβ peptides are generated in early endosomes and sorted to multivesicular bodies (MVBs) in APP-expressing neuroblastoma cells and (ii) the fusion of MVBs with the plasma membrane mediates the release of exosomes loaded with Aβ." (PMID 25741766, 2015). "Therefore, we first examined the effect of high glucose on APP expression in human neuroblastoma cells." (PMID 23894546, 2013). "To examine whether the increase in full-length APP protein induced by high glucose treatment was via upregulation of APP gene transcription, we measured APP promoter activityin human neuroblastoma SH-SY5Y cells treated with 10 or 25 mM glucose." (PMID 23894546, 2013). "Moreover, HSV-1-induced PKR activation in neuroblastoma cells and peripheral nervous tissue from infected mice has been suggested to increase the amyloidogenic APP processing and Aβ production by promoting BACE1 translation via eIF2α phosphorylation." (PMID 22899188, 2012). "Importantly, NF-κB activation in Sw-APP transfected neuroblastoma cells diminished with adiponectin treatment in parallel with its protective effect against cytotoxicity under oxidative stress." (PMID 23300647, 2012). "In this study, we measured the activation of α-secretase APP processing and PKC-α, -δ, and -ε induced by the benzolactam-APP modulator TPPB and bryostatin-1 in the neuroblastoma cell line SH-SY5Y which expresses APP and α- and β-secretase processing mechanisms." (PMID 22700373, 2012). "Furthermore, a cluster of four E4BP4 sites in intron 4 of human APP is shown to be epigenetically marked with H3K9Ac in a human neuroblastoma cell-line that expresses APP." (PMID 22947103, 2012). "To test whether APP and APP-CTFs can also be reduced through this mechanism, we induced autophagy in B103 rat neuroblastoma cells which lack endogenous rat APP and are stably transfected with wildtype human APP695 (B103/hAPP)." (PMID 20559548, 2010). "In order to determine whether Aβ from other cell types had similar effects, media from the APP over-expressing human neuroblastoma SH-SY5Y cells (SKAPP cells) and its parental cell line SH-SY5Y were used for the incubation with tumor cells." (PMID 19480719, 2009).